MGMT (O-6-methylguanine-DNA methyltransferase)
Diseases named in the same sentence as MGMT in open-access papers (continued):
Sharing a sentence is not in itself a finding about the gene and the disease.
glioblastoma (continued). "In adult glioblastoma, introduction of combined chemoradiotherapy of concomitant and adjuvant temozolomide (TMZ) and radiotherapy has provided a modest survival benefit, particularly in patients with an epigenetically silenced O6-methylguanine-DNA-methyltransferase (MGMT) gene." (PMID 19365568, 2009). "Moreover, we investigated the methylation status of the DNA repair protein gene O6-methylguanine-methyltransferase (MGMT), which is a marker of resistance to chemotherapeutic alkylating agents, including temozolomide (TMZ), in high-grade gliomas, particularly glioblastomas." (PMID 19830138, 2009). "Interestingly, inhibitors of DNA methylation and histone deacetylation failed to increase MGMT protein levels in the transformed astrocyte cells as well as cultured glioblastoma cell lines, whereas the treatment partially restored mRNA levels." (PMID 17547775, 2007). "Human glioblastoma cells can acquire resistance rapidly or over time; therefore, a speculative explanation for the higher IC50 value of the U-87 MG cell line in this study is that these cells may have been expressing, singularly or in combination, MGMT, BER, and APNG proteins." (PMID 39457529, 2024). "Therefore, glioblastoma can be divided into two categories based on whether or not there is methylation of the MGMT promoter." (PMID 38681199, 2024). "MGMT shows the webtool’s ability to highlight genes that show profound impact and significance in glioblastoma (GBM) but not low-grade glioma (LGG)." (PMID 37454191, 2023). "An antiangiogenetic activity may be preponderant in glioblastoma, while a cytotoxic effect is more relevant in LMS; MGMT methylation could overcome the repair mechanism role in glioblastoma, resulting in an impairment of angiogenesis, and would not be able to counteract tumor cell proliferation." (PMID 37371106, 2023). "For example, the Stupp protocol, which is the current standard of care for glioblastoma, recommends temozolomide as part of the treatment regimen for patients with MGMT promoter methylation, while patients without MGMT promoter methylation may benefit from alternative treatment options." (PMID 37894355, 2023). "While relative cerebral blood volume (rCBV) may be diagnostic and prognostic for survival in glioblastoma (GBM), changes in rCBV during chemoradiation in the subset of newly diagnosed GBM with subtotal resection and the impact of MGMT promoter methylation status on survival have not been explored." (PMID 35371980, 2022). "These beneficial features might also contribute to the observed median OS of 43 months for the subgroup of non-obese patients with MGMT methylated glioblastoma, comparing favorably to a recent study on the use of immune checkpoint inhibitors in MGMT methylated glioblastoma." (PMID 35704157, 2022). "O6-Methylguanine-DNA-methyltransferase (MGMT) promoter methylation was shown in many studies to be an important predictive biomarker for temozolomide (TMZ) resistance and poor progression-free survival in glioblastoma multiforme (GBM) patients." (PMID 35927323, 2022). "However, patients with a methylated MGMT promoter, glioblastoma, and no baseline corticosteroid use may potentially derive a benefit from treatment with immune checkpoint inhibition." (PMID 34576141, 2021). "Treatment for the lethal primary adult brain tumor glioblastoma (GBM) includes the chemotherapy temozolomide (TMZ), but TMZ resistance is common and correlates with promoter methylation of the DNA repair enzyme O-6-methylguanine-DNA methyltransferase (MGMT)." (PMID 33945569, 2021). "Hypermethylation of the MGMT promoter is considered a predictive biomarker for the response to temozolomide (TMZ), an alkylating agent playing a crucial role in the treatment of glioblastoma multiforme (GBM)." (PMID 34830407, 2021). "However, patients with methylated-O6-methylguanine DNA-methyltransferase (MGMT) promoter glioblastoma and no baseline corticosteroid use may potentially benefit from treatment with ICBs." (PMID 34576141, 2021).
glioblastoma (continued). "The most common and aggressive grade IV, glioblastoma (GBM) typically does not have IDH mutations, nonetheless, frequent intratumoral MGMT promoter methylation is found in these patients." (PMID 33919732, 2021). "Several studies indicated that O6-methylguanine-DNA methyltransferase (MGMT) gene promoter methylation reported in 30-60% of glioblastomas can enhance the response to TMZ, which has been proven to be a prognostic biomarker in GBM patients." (PMID 33029531, 2020). "Therefore, the question whether glioblastoma with vs. without MGMT promoter methylation have a different anatomical localization remains unanswered." (PMID 32477929, 2020). "In the glioblastoma multiforme, it was found that miRNA-370-3p affected the sensitivity of GBM cells to TMZ via MGMT expression, which was not identified in the PCNSL." (PMID 30712191, 2020). "However, unlike glioblastomas lacking one copy of chromosome 10 where MGMT is located, IDHmt lower-grade gliomas usually retain both copies and MGMT may not be completely silenced." (PMID 31968687, 2020). "However, in contrast to these findings, there are also studies that found the reverse pattern of hemispheric lateralization, in which glioblastoma with MGMT methylation were located more frequently in the right hemisphere, while those without MGMT methylation lateralized to the left hemisphere." (PMID 32477929, 2020). "MGMT analysis, also showed that the high level group had longer survival time compared to the low level group, perhaps due to epigenetically silenced MGMT treated with radiotherapy and alkylating chemotherapy may improve the survival of patients with glioblastoma without MGMT expression." (PMID 29100349, 2017). "The O6-methylguanine methyltransferase (MGMT) gene is frequently unmethylated in patients with glioblastoma (GBM), rendering them non-responsive to the standard treatment regime of surgery followed by concurrent radiotherapy (RT) and temozolomide." (PMID 28314386, 2017). "In other glioblastoma sub-cohorts, the clinical utility of MGMT testing is lower and at present does not have direct implications for clinical management, although knowledge of the MGMT promoter methylation status may support prognostic considerations that influence indirectly patient management." (PMID 24359605, 2014). "The most comprehensive glioblastoma dataset with over 200 samples is from The Cancer Genome Atlas, widely used for hypothesis generation and validation in brain tumor research; however, the MGMT methylation status has not yet been annotated." (PMID 22810491, 2012). "The purpose of this study was to determine the relationship between the MGMT status, determined by means of several techniques and methods, and the cytotoxic response to TMZ in 11 glioblastoma multiforme (GBM) cell lines and 5 human tumour cell lines of other origins." (PMID 20517307, 2010). "This thalamic glioblastoma WHO grade 4, MGMT methylated, EGFR non-amplified, shows clear differences compared to the previous case, on multiparametric MRI." (PMID 40227555, 2025). "The case of a 38-year-old female patient shows a frontal glioblastoma WHO grade 4, with involvement of the genu of the corpus callosum, MGMT unmethylated, EGFR non-amplified." (PMID 40227555, 2025). "Of note, a recent phase III trial showed that TMZ did not add any benefit in the treatment of IDH wildtype glioblastoma (new WHO 2021 classification) compared with radiotherapy alone, regardless of MGMT promoter status." (PMID 38791053, 2024). "MGMT-methylated glioblastomas have significantly lower ADC values, as compared to the glioblastomas with no MGMT methylation in peritumoral white matter." (PMID 36900177, 2023). "Neuropathological analysis confirmed the diagnosis of glioblastoma, IDH-wildtype, MGMT-promoter not methylated." (PMID 37561227, 2023). "Majority of neuropathological diagnoses were high-grade glioma (glioblastoma, IDH-wild type, MGMT methylation positive or negative) with 191 procedures (43.7%)." (PMID 38074655, 2023).
glioblastoma (continued). "The ADC values are used as a potential marker for predicting MGMT and TERT status in glioblastomas; however, without expert consensus." (PMID 36471242, 2022). "There is also increasing evidence to investigate dose-escalated RT in patients with glioblastoma, particularly in subgroups that do not receive TMZ or those who are known to have unmethylated DNA repair enzyme O-6-methylguanine-DNA methyltransferase (MGMT)." (PMID 36371225, 2022). "While there is a sizable literature examining clinical outcomes after glioblastoma re-resection at the time of recurrence, the lack of IDH and MGMT promotor methylation status in these studies rendered comparisons difficult." (PMID 35088050, 2022). "Using a Tet-On glioblastoma cell system, we show that upregulation of MGMT immediately after TMZ completely abrogated apoptosis and CSEN, while induction of MGMT long-term (>72 h) after TMZ did not reduce apoptosis and CSEN." (PMID 35565362, 2022). "A biopsy through a laminectomy Th9 was performed and revealed a Glioblastoma WHO IV (IDH-1 wild type, no MGMT methylation)." (PMID 33094355, 2021). "Standard-of-care treatments for patients with recurrent glioblastoma are not well defined; treatment is selected on the basis of prior therapy, age, KPS, MGMT promoter methylation status and patterns of disease progression." (PMID 33293629, 2021). "For this reason, the patient underwent a second surgical procedure, with a total removal of the lesion, resulted to be again a glioblastoma (WHO IV) and non-methylation status of MGMT gene promoter." (PMID 34067871, 2021). "Though numerous studies have demonstrated that the MGMT promoter methylation status may determine the efficiency of TMZ treatment for the GBM patients, this biomarker has not yet been used in routine clinical practice to guide therapy for glioblastoma." (PMID 33588926, 2021). "In glioblastoma CSCs, epigallocatechin gallate (EGCG) treatment downregulated P-gp overexpression but not that of ABCG2 or O6-methylguanine-DNA methyltransferase (MGMT) and increased the cytotoxic effect of TMZ." (PMID 35330670, 2020). "Extracellular S1P derived from glioblastoma stem-like cells in vitro has also been found to confer resistance to TMZ, independent of MGMT status, emphasizing the importance of S1P levels in GBM." (PMID 31906280, 2020). "Methadone was similar toxic in isogenic MGMT expressing and non-expressing cells, and in LN229 glioblastoma and VH10T human fibroblasts." (PMID 32977591, 2020). "Noteworthy, promoter hypermethylation in MGMT, p16INK4a, TIMP-3 and THBS1 was detected at high frequencies in CSF, serum and tumor tissue, in all glioblastoma patients but not in any of the healthy individuals." (PMID 31284524, 2019). "In glioblastoma, exosomes derived from tumor cells harboring PTPRZ1-MET fusion conferred temozolomide resistance to recipient GBM cells, which was independent of O-6-methylguanine-DNA-methyltransferase levels." (PMID 31597943, 2019). "Previous studies have shown that the human paediatric glioblastoma (WHO grade IV) KNS42 cells are wildtype for PTEN and PIK3CA, histone H3.3 (H3F3A) G34V mutant and have no expression of MGMT." (PMID 28704425, 2017). "First, we determined the basal expression level of MGMT by Western blot analysis of TW1 and TW4 cells and compared it to MGMT levels in two well-characterized glioblastoma cell lines, U251, which is negative, and T98G, which is strongly positive." (PMID 26282951, 2015). "We detected a high steady state mRNA and MGMT protein expression levels in U251MG and T98G, but not in U87MG glioblastoma cells (not shown)." (PMID 24678590, 2014). "To exclude the interference of MGMT on TMZ resistance, we selected two MGMT negative glioblastoma cell lines (U251MG and U87MG) for the current study." (PMID 24265816, 2013). "To study a correlation between promoter methylation and gene expression, we analyzed MGMT, ABCB1 and ABCG2 expression in 20 glioblastoma and 7 non-neoplastic brain samples." (PMID 24380367, 2013).
glioblastoma (continued). "Because all glioblastoma patients receive TMZ as part of the Stupp regimen, the methylation status of the MGMT promoter does not change the therapeutic regime today." (PMID 22390413, 2012). "For example patients suffering from glioblastoma multiforme with a methylated MGMT promoter had a better outcome after therapy with temozolomide (TMZ) than those patients, without a methylated MGMT promoter." (PMID 19274096, 2009). "These include methylated MGMT and EGFR-TKI in glioblastoma, EGFR-TKI and ERCC1 in non-small cell lung cancer and pathologic complete response in breast cancer." (PMID 22275966, 2008). "Glioblastomas of the mesenchymal methylation subtype demonstrated significantly higher median and p90 APTw signal intensity compared with RTK1 and RTK2 subtypes, independent of MGMT status and Ki-67 index." (PMID 42154346, 2026). "When analyzing the cohort of 36 HGG individuals defined as having glioblastoma (GBM) according to WHO CNS5/2021, with IDH-wt per definition, the difference of max APTw, mean, and median APTw between MGMT methylated and non-methylated tumors was found to be non-significant (p = 0.078, 0.885; 0.601)." (PMID 40560010, 2025). "This retrospective cohort study suggests that the combined molecular profiling of MGMT promoter methylation and EGFR amplification may help to delineate prognostically distinct subgroups within the heterogeneous population of patients with IDH-wild-type glioblastoma (GBM)." (PMID 40722305, 2025). "The cohort for the PRIDE trial will consist of patients with glioblastoma who meet the following criteria: isocitrate dehydrogenase wild-type (IDH wt), MGMT non-methylated, aged between 18 and 70 years, and clinically eligible to receive temozolomide (TMZ) and BEV." (PMID 38116137, 2024). "Pie diagrams revealed that the high-risk group predominantly included clinical features associated with poor prognosis, such as higher grades (Grade3, Grade4), 1p/19q non-codel, unmethylated MGMT promoter, wild-type IDH status, glioblastoma histology, CL and ME Transcriptome subtype." (PMID 38022537, 2023). "The O6-methylguanine-DNA-methyltransferase (MGMT) can resolve some of the TMZ-induced alterations and thus mediate survival, but is frequently found not to be expressed in approximately half of all glioblastoma cells, i.e., about 45% of patients considered to benefit from TMZ." (PMID 34485282, 2021). "In glioblastomas, nuclear Survivin was shown to predict poor survival after radiotherapy and combined radio-chemotherapy —predictive value for TMZ therapy alone, in MGMT-negative tumors, has not been accessed yet." (PMID 34100981, 2021). "Although in glioblastoma, the efficacy of TMZ is strongly related to the level of O6-methylguanine-DNA methyltransferase (MGMT) promoter hypermethylation, it is not clear whether a similar relationship exists in MPP." (PMID 32132978, 2020). "We further observed that ALDOC significantly lowered mRNA expression in the glioblastoma compared with the non-tumor part, the non G-CIMP compared with the G-CIMP group, and unmethylated MGMT compared with MGMT methylated patients (p < 0.0001, p = 0.0019, and p = 0.0356, respectively)." (PMID 31450822, 2019). "MGMT promoter methylation is a common feature of IDH1/2 mutant/G-CIMP positive glioma, however, is less prevalent in G-CIMP negative tumors, such as primary glioblastoma, where MGMT methylation occurs in approximately 40% of cases." (PMID 25785247, 2015). "Notably, 2 glioblastoma patients (IDH, MGMT positive and IDH negative, MGMT positive, respectively) without residual tumor after resection presented with low blood flow (mTBF<100 ml/100 g/min)." (PMID 24911025, 2014). "However, in contrast to MGMT methylation no data have existed for ABCB1 and ABCG2 promoter methylation in glioblastoma tissue until now." (PMID 24380367, 2013).
glioblastoma (continued). "Our findings suggested a non-linear relationship between OS and MGMT promoter methylation, which implies a varying magnitude of prognostic effect across values of MGMT promoter methylation by pyrosequencing in newly diagnosed IDH wild-type glioblastoma patients treated with chemoradiotherapy." (PMID 35626029, 2022). "Notably, the cell cultures that we have used represent a wide spectrum of genomic backgrounds representing all molecular subtypes of glioblastoma, variable phenotypes and sensitivity to TMZ and RT and includes cultures with and without MGMT promoter-methylation." (PMID 33765907, 2021). "Regardless of the absence of a survival benefit, the tumour MGMT activity results lend validity to the basic premise of the RTOG 0525 trial and other ongoing trials using dose-intense temozolomide regimens in the treatment of newly diagnosed or refractory glioblastoma." (PMID 20628383, 2010). "However, we could detect a significant negative correlation between MGMT promoter methylation and MGMT expression, a markedly elevated MGMT and ABCB1 promoter methylation in glioblastoma specimens and a significant correlation between MGMT methylation and the MGMT C-56 T polymorphism." (PMID 24380367, 2013).